FAM138D (family with sequence similarity 138 member D)
Synonyms: F379
Gene: Long non-coding RNA gene on chromosome 12 (36,602 to 38,133, reverse strand). Ensembl gene ENSG00000249054.
Diseases named in the same sentence as FAM138D in open-access papers:
FAM138D is named in the same sentence as 2 diseases in open-access papers, as found by Europe PMC text mining. Sharing a sentence is not in itself a finding about the gene and the disease. The quoted sentences say what the papers report.
gynecologic cancers (1 paper, 2020). "The recurrent CNV events shared by gynecologic cancers are predicted to cause amplifications of retinal proteins FAM138D and FAM138E, and deletions of genes associated with IFN-α/β signaling, which can be viewed as a strategy of immune evasion." (PMID 33194730, 2020).
FAM138D also shares sentences with these, for which no sentence is quoted: tumor (1 paper).